ZNF217 (zinc finger protein 217)
Diseases named in the same sentence as ZNF217 in open-access papers (continued):
Sharing a sentence is not in itself a finding about the gene and the disease.
keloid (5 papers, 2016 to 2022). An irregularly shaped, elevated mark on the skin caused by deposits of excessive amounts of collagen during wound healing. "By positively regulating ZNF217 expression after decoying miR-182-5p, the lncRNA HOXA11-AS regulates the miR-182-5p/ZNF217 axis to induce the proliferation and migration of keloid fibroblasts in vitro, while promoting keloid formation and growth in mouse." (PMID 36551531, 2022). "The results also indicated that lncRNA-ATB governed the autocrine secretion of TGF-β2 in KFs by partially downregulating the ZNF217 expression via miR-200c, posing a signaling axis consisting of lncRNA-ATB/miR- 200c/ZNF217/TGF-β2 in keloid." (PMID 33243301, 2020). "In this study, we showed that lncRNA-ATB and ZNF217, a transcriptional activator of TGF-β, were overexpressed and miR-200c, which targets ZNF217, was under-expressed in keloid fibroblasts." (PMID 27090737, 2016). "Using immunohistochemistry and quantitative RT-PCR analysis, we showed that lncRNA-ATB and ZNF217, a transcriptional activator of TGF-β, were overexpressed and miR-200c, which targets ZNF217, was under-expressed in keloid tissue and keloid fibroblasts." (PMID 27090737, 2016). "Collectively, our study provides a possible novel signaling axis involving lncRNA-ATB/miR-200c/ZNF217/TGF-β2 in keloid fibroblasts." (PMID 27090737, 2016). "All these results suggest that lncRNA-ATB promotes the autocrine secretion of TGF-β2 in keloid fibroblasts via a signaling loop involving lncRNA-ATB/miR-200c/ZNF217/TGF-β2." (PMID 27090737, 2016). "To confirm this finding, we next evaluated ZNF217 protein and mRNA expression in keloid tissue and normal skin tissue by Western blotting and qRT-PCR, respectively." (PMID 27090737, 2016). "The results showed that ZNF217 was overexpressed in keloid fibroblasts at both the protein and mRNA levels, compared to levels in normal skin tissue." (PMID 27090737, 2016). "The transfection of ZNF217 siRNA decreased the expression of ZNF217 by 1.8-fold change compared with control lentivirus-infected keloid fibroblasts." (PMID 27090737, 2016). "By signal intensity analysis, we found that ZNF217 expression was significantly increased in keloid tissue compared with normal skin tissue (P = 0.013)." (PMID 27090737, 2016). "To further investigate whether the autocrine secretion of TGF-β2 is regulated by ZNF217, we used a ZNF217 siRNA delivery system to stably transfect keloid fibroblasts." (PMID 27090737, 2016). "Collectively, these findings suggest that downregulation of ZNF217 may decrease the autocrine section of TGF-β2 in keloid fibroblasts." (PMID 27090737, 2016). "Altogether, these data suggest that ZNF217 is overexpressed in keloid tissue and fibroblasts." (PMID 27090737, 2016). "To ascertain whether this observed effect depends on regulation of the 3′-UTR of ZNF217 by miR-200c, we constructed a luciferase reporter containing the 3′-UTR of ZNF217 (pmirGLO-ZNF217) and transfected it into keloid fibroblasts." (PMID 27090737, 2016). "To test this hypothesis, in the present study, we detected the expression of lncRNA-ATB, miR-200c, and ZNF217 in keloid tissue and keloid fibroblasts." (PMID 27090737, 2016). "During the process of keloid progression, the oncogenic lncRNA-ATB is activated and contributes to the imbalance between miR-200c and ZNF217, resulting in abnormal TGF-β expression." (PMID 27090737, 2016). "Our results provide the first evidence that in keloids, lncRNA-ATB governs autocrine secretion of TGF-β2, at least in part, by downregulating the expression level of ZNF217 via miR-200c." (PMID 27090737, 2016). "Through gain- and loss-of-function studies, we examined the effect of lncRNA-ATB on autocrine secretion of TGF-β2 in keloid fibroblasts as well as the interactions among TGF-β2, lncRNA-ATB, miR-200c, and ZNF217." (PMID 27090737, 2016).
keloid (continued). "Given that TGF-β signaling is elevated in keloids, we hypothesized that lncRNA-ATB might suppress the autocrine secretion of TGF-β2 by targeting ZNF217 via miR-200c in keloid fibroblasts." (PMID 27090737, 2016). "Because lncRNA-ATB and TGF-β2 reciprocally regulate each other in keloid fibroblasts, we wondered whether lncRNA-ATB could modulate ZNF217 expression." (PMID 27090737, 2016).
leukemia (5 papers, 2022 to 2025). A malignant (clonal) hematologic disorder, involving hematopoietic stem cells and characterized by the presence of primitive or atypical myeloid or lymphoid cells in the bone marrow and the blood. "Employing bioluminescence imaging to track leukemia burden, we observed that ZNF217 depletion significantly suppressed B-ALL progression in both the PDX model and the xenograft model." (PMID 40093906, 2025). "In a parallel vein, another study knocked down zinc finger protein 217 (ZNF217) in B-ALL PDXs and found that leukemia progression was prominently impeded." (PMID 40510031, 2025).
gastric cancer (4 papers, 2011 to 2023). A primary or metastatic malignant neoplasm involving the stomach. "These amplifications have been seen in prior studies in gastric cancer along with amplification of 20p for which ZNF217 and TNFRSF6B have been suggested as candidate driver genes." (PMID 21781349, 2011). "Still, ZNF217 amplification has an adverse prognostic implication in breast and gastric cancer." (PMID 29986747, 2018). "In addition, ZNF217 expression may be a novel prognostic biomarker in gastric cancer." (PMID 34712617, 2021).
glioblastoma (4 papers, 2010 to 2022). The most malignant astrocytic tumor (WHO grade IV). "In glioblastoma, uveal melanoma and soft tissue sarcoma, again, an inverse correlation between ZNF217 expression levels and DNA methylation status was shown to exist." (PMID 36551531, 2022). "In glioblastoma and BCa, the hypoxia-induced HIF1α and HIF2α TFs contributed to the maintenance of stem cells by upregulating ZNF217 expression through a yet undiscovered mechanism." (PMID 36551531, 2022). "In glioblastoma versus control brain, hypomethylation at the ZNF217 promoter was paired with increased ZNF217 expression levels." (PMID 36551531, 2022). "Hypomethylation of the ZNF217 promoter and ZNF217 overexpression were inversely correlated (p = 6 × 10−4) in glioblastoma but not in normal brain tissue." (PMID 26431164, 2015).
glioma (4 papers, 2015 to 2025). A benign or malignant brain and spinal cord tumor that arises from glial cells (astrocytes, oligodendrocytes, ependymal cells). "High ZNF217 mRNA levels were present in glioma samples compared to normal tissue and associated with poor outcome (univariate analysis, p < 0.001)." (PMID 26431164, 2015). "ZNF217 is a candidate oncogene located on chromosome 20q13.2, a region that is frequently amplified in many tumors, including those of the breast, colon, glioma, ovarian and prostate." (PMID 27768596, 2016). "As Aurora-A may regulate self-renewal capacity in glioma-initiating cells via stabilization/activation of β-catenin/Wnt signaling, it might also be involved in ZNF217-driven maintenance of a stem-like phenotype." (PMID 26431164, 2015). "Interestingly, ZNF217 expression was induced by hypoxia in a HIF-dependent manner in glioma cells." (PMID 27590511, 2016).
lung carcinoma (4 papers, 2010 to 2025). "ZNF217 mRNA was further demonstrated to be a direct target for miR-211-3p, and ZNF217 overexpression was sufficient to reverse the inhibitory impact of miR-211-3p on the proliferation or the migration of lung cancer cells." (PMID 36551531, 2022).
metastatic disease (3 papers, 2022 to 2025). "Among patients with T3 stage tumors, we discovered that CTNNB1 and ZNF217 mutations were mainly present in patients who were absent of metastatic disease." (PMID 36439454, 2022).
acute myeloid leukemia (2 papers, 2024 to 2025). Acute myeloid leukemia (AML) is a group of neoplasms arising from precursor cells committed to the myeloid cell-line differentiation. "The purified compounds were tested on nucleophosmin-mutated acute myeloid leukemia and other hematological cancer cell lines to assess their effects on the cell cycle, cell viability and apoptosis, and the expression of ZNF217." (PMID 39770403, 2024). "Using ChIP-seq data, we identified the involvement of the SE-related gene ZNF217 in acute myeloid leukemia (AML), in which its functional role and underlying mechanism remain unclear." (PMID 40083704, 2025).
esophagitis (2 papers, 2022 to 2024). An acute or chronic inflammatory disease affecting the esophageal wall. "In particular, ZNF217 amplification was associated increased risks of developing severe (grade 3 or higher) pneumonitis and esophagitis." (PMID 35912186, 2022). "Similarly, ZNF217 amplification was associated with severe pneumonitis and esophagitis (grade 3 or higher; OR=7.5 [95% CI, 2.0-28.0], P=0.003), as well as severe radiation-induced pneumonitis (OR=4.9 [95% CI, 1.3-18.2], P=0.02)." (PMID 35912186, 2022). "MTHFR (rs1801133), NQO1 (rs1800566), ZNF217 and POLD1 were risk alleles related to a higher susceptibility to pneumonitis and esophagitis." (PMID 38255239, 2024). "Moreover, through their roles in genome integrity and replicative fidelity, somatic alterations in ZNF217 and POLD1 might also serve as risk predictors of high-grade pneumonitis and esophagitis." (PMID 35912186, 2022).
ovarian clear cell cancer (2 papers, 2018 to 2024). An invasive malignant neoplasm that arises from the ovary and is characterized by a predominance of clear and hobnail malignant epithelial cells. "In addition, WES showed that it harbors concurrent ARID1A–PIK3CA mutations and SPOP mutation, also with ZNF217 amplification, which will be an ideal tool for mechanism research of ovarian clear cell carcinoma." (PMID 29986747, 2018). "With regards to ovarian clear cell carcinomas, the screening for mutations in the genes of ARID1A, PIK3CA, and ZNF217, can be judged as an inadequate prognostic marker." (PMID 37548940, 2024).
prostate tumor (2 papers, 2016 to 2021). "Our current findings suggested the expression of ZNF217 was transcriptional activated by MAZ in prostate tumor cells." (PMID 27768596, 2016). "Seven regulators, including IGF2BP2, METTL3, METTL16, ZNF217, ZC3H13, RBM15B, and PRRC2A, exhibited significant correlations between CNVs and gene expression levels in prostate tumors." (PMID 34899855, 2021). "In summary, this study overall deciphers a critical role of ZNF217 in inhibiting FPN expression and then restraining iron egress in prostate tumor cells." (PMID 27768596, 2016).
Alzheimer disease (1 paper, 2022). A progressive, neurodegenerative disease characterized by loss of function and death of nerve cells in several areas of the brain leading to loss of cognitive function such as memory and language. "Interestingly, a lncRNA SNHG1/miR-361-3p/ZNF217 axis has been identified in a model of Alzheimer disease, where lncRNA SNHG1 absorbs miR-361-3p and where ZNF217 mRNA is a direct target for miR-361-3p." (PMID 36551531, 2022).
embryonic carcinoma (1 paper, 2017). "The SNV is in the first intron of PTGIS, overlapping DNase I hypersensitivity regions, potential ZNF217 transcription factor binding sites and H3K36me3 histone mark signatures in the NT2-D1 (pluripotent embryonic carcinoma) cell line." (PMID 28448578, 2017).
head and neck squamous cell carcinoma (1 paper, 2019). A squamous cell carcinoma that arises from any of the following anatomic sites: lip and oral cavity, nasal cavity, paranasal sinuses, pharynx, larynx, and salivary glands. "Freier at al reported that 6.2% of patients with head and neck squamous cell carcinoma exhibited ZNF217 gene amplification." (PMID 30872783, 2019).
liver cancer (1 paper, 2022). An epithelial or non-epithelial malignant neoplasm that arises from the liver. "The expression level of miR-101 was decreased and acted as a negative regulator of ZNF217 in liver cancer, which could not only suppress proliferation but also inhibit the invasion of liver cancer cells." (PMID 36497343, 2022). "MiR-101 could also inhibit the proliferation of liver cancer cells by targeting zinc finger protein 217 (ZNF217), mitogen-activated protein kinases (MAPK)/extracellular signal-regulated kinase (ERK) signaling pathways, and hepatocyte growth factor (HGF)/c-MET axis." (PMID 36497343, 2022).
lymphoma (1 paper, 2023). A malignant (clonal) proliferation of B- lymphocytes or T- lymphocytes which involves the lymph nodes, bone marrow and/or extranodal sites. "In vitro, knockout of ZNF217 led to changes in chromatin accessibility interfering with binding motifs for crucial lymphoma-associated transcription factors." (PMID 37648814, 2023). "IGLL5, which has been described as frequently mutated in other lymphomas, was identified as significantly downregulated in ZNF217 altered specimens." (PMID 37648814, 2023). "Using lymphoma cell lines, we demonstrate that ZNF217 interacts with chromatin modifying proteins, most notably LSD1 and CoREST." (PMID 37648814, 2023). "In order to gain functional information about ZNF217 in lymphoma, we analyzed the ZNF217 status in cell lines of GC origin." (PMID 37648814, 2023). "To analyze the role of ZNF217 in GC-derived aggressive lymphoma, we therefore selected two lymphoma cells lines without ZNF217 deletions/mutations, L-428 and RC-K8." (PMID 37648814, 2023).
malignant peritoneal mesothelioma (1 paper, 2025). An aggressive malignant mesothelioma that arises from the peritoneum. "Recently, pediatric malignant peritoneal mesothelioma cases have been genetically studied, with alterations observed in ALK, EWSR1, FUS1, YY1, or in AURKA, AURKC, HLA-1B, ZNF-217, OR5F1, and MEN1 genes, but not in BAP1." (PMID 40725095, 2025).
melanoma (1 paper, 2021). A malignant, usually aggressive tumor composed of atypical, neoplastic melanocytes. "We show that the relative baseline levels of Kdm4b and Znf217 (a Kdm1a coactivator), determine differentiation state-specific sensitivity of melanoma cells to their corresponding inhibitors." (PMID 33750776, 2021). "Together, these data demonstrate that the sensitivity of BRAF-mutant melanoma cells to SP2509 and JIB-04 can be predicted based on their differentiation state (Ngfr versus Axl) and the relative levels of Znf217 and Kdm4b proteins." (PMID 33750776, 2021). "While Kdm1a protein levels did not significantly correlate with melanoma differentiation state, Znf217 was among the top 4% proteins that correlated with the expression of Axl relative to Ngfr." (PMID 33750776, 2021).
metastatic cancer (1 paper, 2023). A carcinoma which has spread from the original site of growth to another anatomic site. "In metastatic cancer, ZNF217 amplification ranks among the most frequent genetic alterations and its overexpression was reported to be associated with poor outcome, suggesting an oncogenic function." (PMID 37648814, 2023). "ZNF217, located on chromosome 20q13.2, has also been found among the 20 most frequently amplified genes in metastatic cancer." (PMID 37648814, 2023).
metastatic colorectal cancer (1 paper, 2025). "Additionally, a study identified ZNF217 with increased mutation frequency after anti‐EGFR therapy in metastatic colorectal cancer patients, while a mutation in ZNF217 and low TMB in this study were found to be significantly associated with treatment response." (PMID 39712455, 2025).
ovarian hyperstimulation syndrome (1 paper, 2017). A complication of ovulation induction in infertility treatment. "Zinc finger gene 217 (ZNF217) is a candidate gene of polycystic ovary syndrome (PCOS) which is vulnerable to ovarian hyperstimulation syndrome (OHSS)." (PMID 28607476, 2017).
ovarian serous carcinoma (1 paper, 2015). "Later, ZNF217 amplification was reported not in ovarian serous carcinoma, but in CCC." (PMID 25658832, 2015).
ovarian tumors (1 paper, 2025). "Consistent with our in vitro data, patients with ovarian tumors that express higher ZNF217 levels were less responsive to chemotherapy containing platinum-based drugs and paclitaxel." (PMID 41345234, 2025).
pancreatic cancers (1 paper, 2020). "Notably, the transcription factor zinc-finger protein 217 (ZNF217) is an oncogenic protein that is overexpressed in several tumors, including breast 33, ovarian 34, colon, and pancreatic cancers." (PMID 32226503, 2020).
rheumatoid arthritis (1 paper, 2020). A chronic, systemic autoimmune disorder characterized by inflammation in the synovial membranes and articular surfaces. "Studies have shown that ARMCX5 can be activated by binding to the oncogene ZnF217 and ARMCX6 upexpressed at least 2-fold in peripheral blood monocytes of rheumatoid arthritis patients compared to those identified using oligonucleotide array." (PMID 32685472, 2020).
sarcoma (1 paper, 2013). A usually aggressive malignant neoplasm of the soft tissue or bone. "As differentiation markers for the UPS/MFS cluster (sarcoma cluster 4) DMRT2, ZNF217 and CDKN2A were selected for comparison with sarcoma cluster 1 (mainly DDLS samples), sarcoma cluster 2 (LMS samples) and sarcoma cluster 4 (mainly PLS samples), respectively." (PMID 24345474, 2013).
serous carcinoma (1 paper, 2015). "Moreover, in CCC samples, DNA copy number gains are frequently observed at chromosome 20, which harbours a potential oncogene, ZNF217 (Zinc Finger Protein 217), but this alteration is not observed in serous carcinoma samples." (PMID 25658832, 2015).
small cell lung carcinoma (1 paper, 2021). Small cell lung cancer (SCLC) is a highly aggressive malignant neoplasm, accounting for 10-15% of lung cancer cases, characterized byrapid growth, and early metastasis. "Finally, we show that SMAD3, ZNF217, KLF13, GATA2, GATA3, KLF7, and PHOX2B are components of CRCs in other cancers, including DLBCL, pancreatic, gastric, breast, and small cell lung cancer." (PMID 35201514, 2021).
soft tissue sarcoma (1 paper, 2022). A malignant neoplasm arising from muscle tissue, adipose tissue, blood vessels, fibrous tissue, or other supportive tissues excluding the bones. "In a study aiming at identifying DNA methylation profiles in soft tissue sarcoma subtypes, ZNF217 locus showed DNA hypomethylation and was part of a minimal set of eight CpG sites, allowing the discrimination of the different sarcoma subtypes." (PMID 36551531, 2022).
uterine cancer (1 paper, 2025). Primary or metastatic malignant neoplasm involving the uterine corpus and/or the cervix. "This strategy holds potential for broader application across various cancers, including brain, breast, colon, gastric, liver, ovarian, pancreatic, and uterine cancers, in which ZNF217 has been reported to be amplified and correlates with a worse prognosis 22-33." (PMID 40093906, 2025). "The zinc finger protein 217 (ZNF217) has emerged as a potential oncogene across a broad spectrum of cancers, including brain, breast, liver, lung, and uterine cancers 22-33." (PMID 40093906, 2025).